CLDN1 (claudin 1)
Diseases named in the same sentence as CLDN1 in open-access papers (continued):
Sharing a sentence is not in itself a finding about the gene and the disease.
coccidiosis (3 papers, 2021 to 2023). A parasitic infection caused by Coccidia. "The linear increase of Claudin 1, cationic amino acid transporter, glucose transporter 1, and L-type amino acid transporter genes was associated with increased severity of coccidiosis (P < 0.01)." (PMID 34108017, 2021). "Studies focusing on intestinal integrity in coccidiosis have found an increase in intestinal permeability and an upregulation of the tight junction proteins, claudin-1 (CLDN1), and junctional adhesion molecule-2 (JAM2) in a mixed-species Eimeria infection." (PMID 37680750, 2023). "E. maxima challenge did not change the gene expression of other TJ proteins such as claudin-1, JAM-2, occluding, and ZO-1, most likely due to the fact that the challenge resulted in mild coccidiosis as determined by a lesion score of only 1.5." (PMID 35812452, 2022).
colonic adenoma (3 papers, 2023 to 2024). "For example, CLDN1 has recently been proposed as a target for immunofluorescence targeting for improved visualization of colon adenomas and cancers in mouse models." (PMID 38540693, 2024). "A near-infrared tagged peptide, claudin-1 was recently utilized to detect endoscopically pre-malignant colonic adenomas." (PMID 37799140, 2023). "Claudin-1 was found to be overexpressed in the original colonic adenoma from the patient specimens." (PMID 38337789, 2024).
enteropathy (3 papers, 2016 to 2024). "During the enteropathy caused by NSAIDs, we observed alterations in the expression of critical tight junction proteins, ZO-1, CLDN-1, and OCLN." (PMID 34684313, 2021).
esophageal cancer (3 papers, 2021 to 2025). A primary or metastatic malignant neoplasm involving the esophagus. "According to our data, low CLDN1 expression was previously associated with PTX-resistance in esophageal cancer cells." (PMID 36291810, 2022).
gastric adenocarcinoma (3 papers, 2013 to 2020). "In this study we identified CLDN1 as one of the most consistently up-regulated genes in GC and a strong correlation between up-regulation of CLDN1 and reduced survival in 20 patients with gastric adenocarcinomas." (PMID 24321518, 2013). "However, another study showed that in comparison to CLDN-4, the expression of CLDN-1 was higher in well-to-moderately differentiated gastric adenocarcinomas." (PMID 31952355, 2020).
gastric tumors (3 papers, 2013 to 2016). "Conversely, transcription factor RUNX3, which is a gastric tumor suppressor, upregulates claudin-1 expression by binding to the promoter region of CLDN1 in gastric epithelial cells." (PMID 24009024, 2013). "We suggested that the increased expression of these genes in the gastric tumors may represent early events in gastric carcinogenesis mediated by chronic H. pylori infection, in particular claudin-1 (CLDN1) and interleukin-8 (IL-8)." (PMID 26984265, 2016).
Glucose intolerance (3 papers, 2017 to 2025). Glucose intolerance (GI) can be defined as dysglycemia that comprises both prediabetes and diabetes. "A “lower” cluster contained elevated levels of Firmicutes, Bacteroidetes, Actinobacteria, Proteobacteria and Defferibacteres, and was associated with increased weight gain, glucose intolerance, triglyceride accumulation, and decreased claudin-1 expression." (PMID 34357150, 2021). "In addition, K6 probiotics significantly mitigated SD-induced weight loss, exercise performance decrement, glucose intolerance, inflammation (TNF-α, IL-1β), tight junction hyperpermeability (Claudin-1, ZO-1), and circadian dysregulation (BMAL-1, CLOCK)." (PMID 40959574, 2025).
Hashimoto thyroiditis (3 papers, 2016 to 2024). An autoimmune disorder caused by the production of autoantibodies against thyroid tissue. "CLDN1 is an essential molecule in tight junctions, CLDN1 was highly expressed in normal thyroid epithelium, but reduced in Hashimoto's Thyroiditis (HT) injured thyroid epithelial cells." (PMID 29351231, 2018).
head and neck squamous cell carcinoma (3 papers, 2021 to 2025). A squamous cell carcinoma that arises from any of the following anatomic sites: lip and oral cavity, nasal cavity, paranasal sinuses, pharynx, larynx, and salivary glands. "In studies of head and neck squamous cell carcinoma, increased Cldn1 expression has been associated with tumor progression through the inhibition of AMP-activated protein kinase activity and the activation of tumor growth factor-β signaling, which promotes tumor growth." (PMID 40361399, 2025). "HDAC inhibitors suppress the proliferation, migration, and invasiveness of head and neck squamous cell carcinoma (HNSCC) by down-regulating the p63-mediated tight junction molecules JAM-A and claudin-1." (PMID 36291586, 2022).
Hypertension (3 papers, 2022 to 2025). The presence of chronic increased pressure in the systemic arterial system. "Accordingly, the expression of miR-3571 was lower during hypertension, with up-regulated CLDN1 protein levels." (PMID 35370461, 2022). "Together, these data suggest that CLDN1 was a downstream target of miR3571 and may be involved in the progression of hypertension." (PMID 35370461, 2022). "This suggests that miR-3571 and CLDN1 may be involved in the progression of hypertension." (PMID 35370461, 2022).
hypopharyngeal squamous cell carcinoma (3 papers, 2017 to 2020). "CLDN-1 has also been shown to be significantly expressed in hypopharyngeal squamous cell carcinoma tissues, suggesting that CLDN-1 is associated with tumor differentiation and lymph node metastasis." (PMID 31330820, 2019). "CLDN-1 was found to be upregulated in hypopharyngeal squamous cell carcinoma (HSCC)." (PMID 31952355, 2020).
idiopathic pulmonary fibrosis (3 papers, 2010 to 2025). Idiopathic pulmonary fibrosis (IPF) is a nonneoplastic pulmonary disease that is characterized by the formation of scar tissue within the lungs in the absence of any known cause. "In addition, the use of Claudin-1-specific monoclonal antibodies in renal, hepatic, and lung fibrosis models showed clear antifibrotic effects, further indicating the role of Claudin-1 as a therapeutic target for tissue fibrosis across organs." (PMID 38587753, 2024). "In our previous study with samples from normal human adult lung, sarcoidosis and idiopathic pulmonary fibrosis (IPF) claudin-3, -4 and -7, but not claudin-1, were positive in normal type II pneumocytes, a finding which is in agreement with the results of the present study." (PMID 20478039, 2010).
invasive carcinoma (3 papers, 2005 to 2024). A carcinoma that is not confined to the epithelium, and has spread to the surrounding stroma. "Claudin-1 expression was reduced in 74% of patients belonging to the>40 years age group (as seen in cyclin D1 expression) and those with grade 2 and grade 3 invasive carcinoma, measuring more than 2 cm in size." (PMID 40034931, 2024). "Claudin 1 positive case had a tumor size of >5 cm, belonged to invasive carcinoma NST and had 4 to 9 lymph nodes positive, although these findings were not statistically significant." (PMID 40034931, 2024). "CLDN1 positivity was also observed in some cell membranes in pure DCIS cases or in the DCIS component of invasive carcinomas." (PMID 15743508, 2005).
liver cirrhosis (3 papers, 2015 to 2024). "Our animal experiment indicated that occludin and claudin-1 decreased during liver cirrhosis development, endotoxin in portal system was also found elevated due to the tight junction dysfunction in liver cirrhotic rats." (PMID 26152281, 2015). "Additionally, this two excellent case control studies indicated occludin, claudin-1 and claudin-2 as the significant altered tight junction proteins during the liver cirrhosis decompensating process." (PMID 26152281, 2015).
lupus (3 papers, 2023 to 2025). "The enrichment of P. distasonis in lupus mice conserved claudin-1 localized to the epithelial cell membrane and was associated with reduced gut permeability and dampened systemic inflammation." (PMID 40761803, 2025). "Lupus mice also showed an altered ileal epithelium localization of the tight junction protein claudin-1." (PMID 40761803, 2025). "Total claudin-1, occludin, and ZO-1 expression was significantly upregulated in the lupus mice and restored in the CLC group." (PMID 40507090, 2025). "In addition, the expression of the blood–brain barrier endothelial cell tight junction proteins claudin-1, occludin, and ZO-1 was abnormally modified in lupus mice and was restored in the CLC group." (PMID 40507090, 2025). "Furthermore, the expression of Tyr-phosphorylated forms of claudin-1, occludin, and ZO-1 was increased in the lupus mice." (PMID 40507090, 2025). "TLR7/8 activation impaired gut integrity in lupus-prone TC mice but not in congenic controls based on the FITC-dextran assay, and it lowered the expression of Claudin-1 between gut epithelial cells and PECAM1 between blood/lymphatic endothelial cells." (PMID 37483626, 2023).
metastatic colorectal cancer (3 papers, 2008 to 2023). "Claudin-1 has been shown to be upregulated in primary and metastatic colorectal cancer that may be important in enhancing the tumorigenicity." (PMID 18781153, 2008).
metastatic melanoma (3 papers, 2020 to 2024). A melanoma that has spread from its primary site to another anatomic site. "Known for its role in cell adhesion, CLDN1 is downregulated in metastatic melanomas compared to benign nevi." (PMID 39367275, 2024). "For example, claudin-1 was found to activate MMP-2 through the activation of the c-Abl-protein kinase Cδ (PKCδ) signaling pathway, while increased secretion of MMP-2 correlated with cytoplasmic expression of claudin-1 in metastatic melanoma cells in a PKC-dependent manner." (PMID 34354941, 2021).
osteosarcoma (3 papers, 2019 to 2023). A usually aggressive malignant bone-forming mesenchymal neoplasm, predominantly affecting adolescents and young adults. "Aberrant expression and mis-localisation (cytoplasmic/nuclear instead of cell-cell junctions) of Claudin-1 is reported in several cancers, such as osteosarcomas and colorectal cancers." (PMID 31467400, 2019). "Importantly, NMD is particularly pronounced in osteosarcomas, and the absence of adequate cell-to-cell adhesions (e.g., CLDN1, CLDN15) and a potent host immune response, makes vitamin D3 a likely candidate for combined immunotherapy." (PMID 37228489, 2023).
ovarian tumor (3 papers, 2009 to 2021). "Since tight junctions are important for spheroid formation, we wanted to determine whether the expression of CLDN1 was associated with spheroid formation and ovarian tumor progression." (PMID 33828978, 2021). "The finding of this study showed that Claudin-1 expression in stage II was higher than its expression in stages I, III, and IV in ovarian tumor sample, and a statistically significant correlation was between the Claudin-1 expression and tumor staging." (PMID 31700829, 2019).
papillary carcinoma (3 papers, 2020 to 2024). A malignant epithelial neoplasm characterized by a papillary growth pattern. "Papillary carcinoma exhibited high expression of both claudin-1 and 4, and claudin-1 expression was higher in patients with nodal disease than in patients without nodal disease." (PMID 39458944, 2024). "The expression of CLDN-1 was significantly different between malignant and benign thyroid neoplasms, and between follicular and papillary carcinomas." (PMID 31952355, 2020). "Similarly, papillary carcinomas showed significantly higher positive CLDN-1 expression." (PMID 31952355, 2020). "In papillary thyroid carcinoma (PTC), CLDN1 is the target of miR-101, and overexpression of CLDN1 can reverse the inhibitory effect of miR-101 on cell migration and invasion." (PMID 36497343, 2022).
thyroid tumor (3 papers, 2020 to 2024). A benign or malignant neoplasm affecting the thyroid gland. "Local injection of these recombinant CPE mutants strongly reduced growth of Cldn1-expressing thyroid tumors in CDX models." (PMID 34503203, 2021). "This article aimed to analyze the expression of claudin-1 and claudin-4 in various thyroid tumors." (PMID 39458944, 2024). "We thereby enabled, as proof of principle, Cldn1‐directed cytotoxic targeting of thyroid tumors." (PMID 31825142, 2020).
ZIKV infection (3 papers, 2020 to 2022). "ZO-1 and Cldn-1 were detected to evaluate the BEB integrity after ZIKV infection." (PMID 33667230, 2021). "However, at 5 dpi, ZIKV infection considerably reduced Cldn-1 expression and disrupted the arrangement." (PMID 33667230, 2021). "In this study, we identified two peptides derived from the N-terminal sequences of claudin-7 and claudin-1, named CL7.1 and CL1.1, respectively, that inhibited ZIKV infection in a panel of human cell lines." (PMID 36040168, 2022). "In the absence of IFN-γ signaling, ZIKV infection induced a smaller reduction in CLDN1 expression." (PMID 33315931, 2020).
alopecia (2 papers, 2019 to 2023). Hair loss usually from the scalp. "These patients have features similar to AD (erythema, dry flaky skin, and patchy alopecia) and severe liver and gallbladder abnormalities that are likely due to the importance of cldn-1 in the integrity of the bile duct barrier." (PMID 36836073, 2023).
Anxiety (2 papers, 2024 to 2025). Intense feelings of nervousness, tension, or panic often arise in response to interpersonal stresses. "ZSSF treatment dramatically reduced anxiety-like behaviors, exerted sedative–hypnotic effects, increased hippocampal 5-HT and 5-HTP, and enhanced intestinal barrier function through inhibiting colon ZO-1, Claudin-1, and Occludin expression and reducing TNF-α, IL-6, and IL-1β levels." (PMID 40077533, 2025).
autoimmune disease (2 papers, 2016 to 2026). A disorder resulting from loss of function or tissue destruction of an organ or multiple organs, arising from humoral or cellular immune responses of the individual to their own tissue constituents. "Among the potential targets, we focused on CLDN1 because it was downregulated in the thyrocytes after infection with LV-has-mir-142 using qRT-PCR and was lost in various autoimmune diseases, including autoimmune thyroid disease." (PMID 27277258, 2016). "Studies have shown that downregulated CLDN1 contributes to autoimmune diseases and particularly impairs the epithelial barrier function in primary cultured human thyrocytes." (PMID 27277258, 2016). "More evidence has shown that CLDN1 expression is downregulated in various autoimmune diseases." (PMID 27277258, 2016).
carcinoma of the esophagus (2 papers, 2022 to 2025). "CLDN1 is localized in the nucleus of oesophageal cancer cells, and its expression is upregulated in oesophageal cancer tissue, which is associated with lymph node metastasis." (PMID 40687428, 2025). "In addition, CLDN1 can induce autophagy and promote oesophageal cancer cell proliferation and metastasis by activating the AMPK/STAT1/ULK1 signaling pathway." (PMID 40687428, 2025). "Conversely, reduced expression of CLDN1 and CLDN7 correlates with invasion and metastases in gastric epithelial cells and carcinoma of the esophagus, respectively." (PMID 36077068, 2022).
celiac disease (2 papers, 2014 to 2016). An autoimmune genetic disorder with an unknown pattern of inheritance that primarily affects the digestive tract. "Celiac disease is characterized by enhanced intestinal paracellular permeability due to alterations of function and expression of tight junction (TJ) proteins including ZO-1, Claudin-1 and Occludin." (PMID 24483336, 2014).
Cerebral ischemia (2 papers, 2018 to 2021). Restriction of arterial blood supply to the brain associated with insufficient oxygenation to support the metabolic requirements of the tissue. "To evaluate intestinal barrier integrity in the first days after brain injury, we examined claudin-1 and occludin expression in the membrane fraction from ileum and colon homogenates 1 and 3 days after cerebral ischemia." (PMID 30510535, 2018). "Cerebral ischemia led to lower levels of structural components of the BBB such as tight junction proteins (occludin, claudin-1 and ZO-1) in the MCAO/R group compared with the sham group (P < 0.001)." (PMID 34857032, 2021).
Co-infection (2 papers, 2022 to 2026). "Co-infection significantly impaired intestinal barrier function, as evidenced by a marked downregulation of claudin-1 messenger RNA (mRNA) expression compared to both single-infection groups, and triggered more intense local and systemic inflammatory responses." (PMID 41782115, 2026). "In the present study, co-infection with CCP also upregulated the mRNA levels of occludin, ZO-1, and claudin-1 in the intestine." (PMID 36496951, 2022).
colorectal tumor (2 papers, 2013 to 2023). "LIN28B/CLDN1/NOTCH3 axis positively correlates with metastatic progression of human colorectal tumors." (PMID 37318881, 2023). "Claudin-1, -3, and -4 are overexpressed in colorectal tumor tissues." (PMID 24204396, 2013).
cutaneous melanoma (2 papers, 2015 to 2017). A primary melanoma arising from atypical melanocytes in the skin. "Stimulation of BEC with CM of ANGPTL4 over-expressing cutaneous melanoma cells down-regulated the expression of CLDN1, a TJ protein involved in cell adhesion." (PMID 29100268, 2017). "Thus hypermethylation of distinct Claudins were frequently reported in human cancers and it will be interesting to analyze the methylation of several Claudin family members (e.g., CLDN1 and CLDN15) in cutaneous melanoma." (PMID 26198249, 2015).
diabetic polyneuropathy (2 papers, 2021). "Claudin-1 is also affected in a later phase in diabetic polyneuropathy." (PMID 34576252, 2021).
Diarrhea (2 papers, 2024 to 2025). Abnormally increased frequency (usually defined as three or more) loose or watery bowel movements a day. "In diarrhea-predominant irritable bowel syndrome, the barrier-disrupting effect with a decrease in TER can be attributed to a downregulation of claudin-1." (PMID 40244215, 2025).
ductal breast carcinoma in situ (2 papers, 2005 to 2023). A carcinoma entirely confined to the mammary ducts. "In a study with ductal breast carcinoma in situ, D’Arcy and coworkers depleted SDC1 in MCF10A cells and observed an upregulation of EMT marker gene expression, including E-cadherin (CDH1), fibronectin-1 (FN1), and claudin-1 (CLDN1)." (PMID 36980680, 2023).
ductal pancreatic adenocarcinomas (2 papers, 2020 to 2025). "Claudin-1 was overexpressed in pancreatic ductal adenocarcinoma and intraepithelial neoplasia compared to normal ducts, and high levels predicted poor prognosis." (PMID 40361399, 2025). "Claudin-1 knockout diminished cell proliferation, migration, invasion, and chemoresistance in pancreatic ductal adenocarcinoma." (PMID 40361399, 2025). "Claudin-1 knockout reduced cell proliferation, migration, invasion, and chemoresistance in pancreatic ductal adenocarcinoma." (PMID 40361399, 2025). "CLDN-1 is expressed by ductal pancreatic adenocarcinomas as well as intra-ductal papillary mucinous pancreatic tumors." (PMID 31952355, 2020). "One study demonstrated that 58% positive CLDN-1 immunostaining in ductal pancreatic adenocarcinomas and intraductal papillary pancreatic tumors." (PMID 31952355, 2020).
enteritis (2 papers, 2022 to 2024). Inflammation of the small intestine. "A large number of in vitro experiments proved that TGEV reduces the protein levels of Claudin-1, Occludin and ZO-1 in IPEC-J2 cells, which is closely related to its cause of viral enteritis, diarrhea and morbidity in piglets." (PMID 36052062, 2022).
epithelial dysplasia (2 papers, 2020 to 2025). "This phenomenon can be observed in our systematic review by the loss of membrane expression of cell adhesion markers such as claudin-1 and, particularly, E-cadherin in cases diagnosed as epithelial dysplasia." (PMID 31967982, 2020).